VEGFA (vascular endothelial growth factor A)
Diseases named in the same sentence as VEGFA in open-access papers (continued):
Sharing a sentence is not in itself a finding about the gene and the disease.
cancer (continued). "As such, we expect more clinical trials testing the combination of VEGFA pathway inhibition and ICB in more diverse cancer types, especially those on which ICB alone is less efficacious." (PMID 35577211, 2022). "Although several studies determined the direct or indirect network between PIK3CA, KDR, GAB1, VEGFA, PLCG, and CRKL and hsa-miR-429 in various cancers, the functional regulation of these genes in Bag-1 deficiency conditions is still needed to elucidate." (PMID 37533517, 2022). "STAT3 was most frequently found in S:E-specific cancer pathways, such as the JAK-STAT pathway, Notch signaling pathway, receptor tyrosine kinase/PDGF signaling pathway, TGF-β signaling pathway, and VEGFA signaling pathway." (PMID 36579559, 2022). "In this study, OTUD6B expression has been unraveled to be positively correlated with most of the 47 immune checkpoint genes in almost all cancers, such as CD276, VEGFA, HMGB1, and TLR4." (PMID 36052059, 2022). "Ma0 cluster was populated in PT and highly expressed VEGFA and SPARC, which are essential macrophage genes that induce angiogenesis and cancer cell migration." (PMID 35184420, 2022). "For example, as a result of the local acidification of the microenvironment, the expression of vascular endothelial growth factor A (VEGF-A) increases, which increases the proliferation of cancer cells." (PMID 35628385, 2022). "Pathway analysis was performed using over-representation analysis of correlated genes, and seven cancer-related pathways (focal adhesion kinase (FAK)/PI3K-Akt, JAK-STAT, Notch, receptor tyrosine kinase/PDGF, TGF-β, VEGFA, and Wnt signaling) were identified." (PMID 36579559, 2022). "MiR-497 was also found to be considerably down-regulated in NSCLC and can suppress angiogenesis, cancer cell proliferation, and invasion by targeting HDGF and VEGFA." (PMID 35918758, 2022). "FABP5 was demonstrated to promote angiogenesis through activating the IL6/STAT3/VEGFA pathway in HCC, or transporting excessive levels of fatty acids into the nucleus of the cancer cells to activate PPARγ thereby up-regulating the expression of VEGF." (PMID 35445019, 2022). "The VEGFA signaling pathway, the MAPK pathway, and cancer transcriptional misregulation were all shown to be upregulated in cancer cells in solid regions, indicating a more invasive phenotype." (PMID 35874770, 2022). "3-O-Acetyloleanolic acid from Vigna sinensis has been reported to inhibit VEGFA and suppress VEGFR1 and VEGFR2 and the phosphorylation of PI3K, FAK, Akt, and ERK1/2, which thereby inhibits angiogenesis and cancer growth." (PMID 35211240, 2022). "Vascular endothelial growth factor-A (VEGF-A) is the activating ligand of the VEGF receptor (VEGF-R), which plays a major role in cancer angiogenesis, and was overexpressed in 53.7% of penile SCC in a retrospective study." (PMID 35800050, 2022). "Our PPI network analysis identified four hub genes (SLC2A1, VEGFA, JUN, and PTGS2) enriched in the cancer-related pathways." (PMID 36482897, 2022). "These macrophages are recruited and polarized into a pro-tumoral phenotype (upregulation of CD206, CD163 and CD209) by CSF-1, CXCL2, VEGFA and CCL18 produced by cancer cells." (PMID 35309358, 2022). "LINC00628 has been reported to inhibit the malignant progression of cancer through different mechanisms, such as binding to EZH2 to regulate the p57 or H3K27me3 level, and interacting with the promoter of LAMA3 or VEGFA." (PMID 35350786, 2022). "These predicted effects rely in the inactivation of key transcription factors (NF-κB, c-FLIP, VEGFA, survivin or BIRC5) involved in resistance to death and inhibition of survival signals in cancer cells." (PMID 35106125, 2022).
cancer (continued). "MRNA expression of SPP1, VEGFA, POSTN, CD44, FOXO1, and RUNX2 genes was significantly change with the cancer stages of the patients." (PMID 36424413, 2022). "Cancer cell exosomes can also transport HOTAIR (HOX transcript antisense RNA) to endothelial cells, thus increasing VEGFA expression to stimulate angiogenesis, explaining why most cancer-cell-derived exosomes can promote angiogenesis." (PMID 36291860, 2022). "In the present study, VEGFA, RRM2, H2AFX, CHEK1, CEP55, CDCA8 and AURKA were significantly upregulated; however, VCL, TPM2 and TPM1 were significantly downregulated in cancer samples of BC." (PMID 34112125, 2021). "Expression increase of VEGFA, PGE2S, COX2, EGFR, and NANOG in cancer cells was characteristic for the increase of resistance, as the sensitizing ratio was the opposite in the principal component analysis." (PMID 33671869, 2021). "As with other cancer types, CRC is also treated with targeted therapy, prepared for affecting predominant markers, such as VEGFA and EGFR." (PMID 35053185, 2021). "Colony-stimulating factor 1 (CSF-1), vascular endothelial growth factor A (VEGF-A), and different CCL were found to act as chemotactic molecules in various cancer." (PMID 33418996, 2021). "VEGFA and FGF2 are both targets of miR-503 in cancer; therefore, miR-503 plays an anti-angiogenic role in tumorigenesis." (PMID 34095461, 2021). "GSEA analyses also revealed several recognized cancer-driving activation pathways in PASC cells, such as VEGFA/VEGFR2 56, 57, glycolysis/gluconeogenesis 58, and oxidative phosphorylation." (PMID 34326696, 2021). "Increased expression of VEGFA, PGE2S, COX2, EGFR, and NANOG in cancer cells was characteristic for the increase of resistance." (PMID 33671869, 2021). "Especially, they significantly decreased VEGFA, phosphorylated erythroblastic oncogene B-2 gene (p-ERBB2), p-AKT and p-VEGFR at the dose of 300 and 400 μg/mL, suggesting that anti-cancer effects were improved with increased dosages." (PMID 33801741, 2021). "Both VEGFA and ANGPT2 have been used as biomarkers for measuring the efficacy of various drugs used in cancer treatment." (PMID 35052372, 2021). "The addition of benign cell lysate resulted in a significant increase of MMP9, VEGFA, ApoE, ANG, and MMP10, and the addition of cancer cell lysate resulted in a significant increase of MMP9, CA9, PAI1, ApoE, A1AT, ANG, and MMP10." (PMID 34204951, 2021). "E2F transcription factors (E2F) control multiple events, including cell cycle as well as cancer metastasis by regulating various genes, such as cell division cycle 6 (CDC6) and VEGFA." (PMID 33435156, 2021). "Cancer cells secrete VEGFA and activate VEGFR2 on their surface to form an autocrine loop, which enables cancer cells to promote their own growth and survival." (PMID 34944605, 2021). "The known roles of VEGFA, ACKR3, IL6 and FYN establish them as the major regulators of cancer pathways cluster in the network." (PMID 34439877, 2021). "The subsequent upregulation of VEGFA mediates the activation of the downstream RAS/RAF/MEK/ERK pathway, resulting in the promotion of cancer cell proliferation, angiogenesis, and EMT." (PMID 34205978, 2021). "eHSP27, released by cancer cells in the TME, induces monocytes to express different cytokines, as IL-10, IL-6, and proangiogenic factors, as prostaglandin E2, VEGFA, IL-8, IL-1β, and TNFα." (PMID 33544155, 2021). "Surprisingly, the TAM subset displaying higher pro-angiogenic functions (VEGFA, SPP1, MARCO) exhibited the higher diversification of markers across different cancer types." (PMID 34572013, 2021).
cancer (continued). "Among the three subtypes, we identified both common (NSC-like and astroependymal-like) and cancer-specific subclusters, such as the immune-reactive subcluster in SE and EPN and the VEGFA+ subcluster in EPN." (PMID 34824203, 2021). "For patient ID 110, this notably included MAP2K2, KIT, VEGFA, A2M, ICAM1 and PLA2G4A, all of which are involved in cancer development." (PMID 34771574, 2021). "Vascular endothelial growth factor A (VEGF) is a prominent cytokine which promotes angiogenesis and a key target of anti-cancer therapies." (PMID 33322601, 2020). "Some of the crucial genes in this overlap include VEGFA, PDGFC and FN1 that were known to be involved in angiogenesis in different types of cancers." (PMID 32720467, 2020). "VEGFA, PTEN, PIP5K1A, CDK1, and CCND1 in the panel are key factors involved in the PI3K/AKT pathways important for cancer survival and metastasis." (PMID 33363151, 2020). "In a mouse model of inflammation-driven cancer and in HCC patients, HCC subclass carrying VEGFA amplification was particularly responsive to VEGFA inhibition and sorafenib treatment." (PMID 32549224, 2020). "Genes and proteins involved in the regulation of cancer cell proliferation and metastasis, such as IL6, IL8, and VEGFA, were similarly regulated under RPM and spaceflight conditions." (PMID 32070055, 2020). "Of note, IGF-1 increases the proliferation of many cancer cells, IL-10, and TGF-β1 inhibits the immune responsiveness of T cells, and VEGFA enhances angiogenesis." (PMID 32908942, 2020). "Expression of LINC00518 was evaluated, together with CDH1 and VEGFA, two known targets of KDM1A in other cancer models." (PMID 33371395, 2020). "It is known that VEGFA directs binding to its receptor VEGFR2 and stimulates angiogenesis, endothelial cell migration, and cancer cell proliferation and survival." (PMID 32564774, 2020). "In this study, the pathway analysis showed that the potential targets such as VEGFA and EGFR were mainly enriched in pathways including proteoglycans in cancer and estrogen-signaling pathway." (PMID 32256653, 2020). "HIF1A and VEGFA (vascular endothelial growth factor A) are the two genes shared by the four diseases in both the HIF-1 signaling pathway and the pathways in cancer." (PMID 30700303, 2019). "In a calibration experiment using cancer cell lines with VEGFA amplification (OE19), VEGFA amplification was robustly detected with a copy number of 9 to 10 (median, 9.7; range, 9.3–10.4)." (PMID 30935424, 2019). "In actuality, several cancers including CRC are known to undergo an angiogenic switch with progression, and anti-VEGFA therapy is currently used." (PMID 31652600, 2019). "More recently, an aberrant increase of IRES-dependent translation of key cancer gene mRNAs has been reported in cancer cells, including the major angiogenic factors FGF1, FGF2 and VEGFA, as well as c-myc and insulin growth factor-like receptor (IGF1R)." (PMID 30791615, 2019). "In cancer cells, FOXO3 has been reported to repress VegfA expression by directly binding to the VegfA promoter region." (PMID 30842454, 2019). "VEGFR1 also has a prominent role in cancer and interestingly, like VEGFB, VEGFA can also signal through this receptor." (PMID 29732375, 2018). "Vascular endothelial growth factor A (VEGF-A) is a key player in blood vessel development and maintenance as well as in several pathological conditions such as cancer and cardiovascular diseases." (PMID 30463374, 2018). "Additional peaks involving important cancer genes such as SOX2, MYC, VEGFA and CDK6 were also found." (PMID 29370817, 2018).
cancer (continued). "Molecular method was based on the analysis of selected genes expression related to hypoxia (HIF1A, ANGPTL4, TGFB1, VEGFA, ERBB3, CA9) or specific for inflammation in hypoxic sites (CCL2, CCL5) at various time points after CT26 cancer cells inoculation." (PMID 30412628, 2018). "By inhibiting vascular endothelial growth factor A (VEGFA) and astrocyte elevated gene-1 (AEG-1), miR-497 suppresses microvessel densities in xenograft cancers." (PMID 29951542, 2018). "Apart from iNOS signaling, some of the well-known key angiogenesis and metastatic transcription factors described in in vivo study, including vascular endothelial growth factor A (VEGFA), have been demonstrated as potential therapeutic targets for cancer." (PMID 30519270, 2018). "HJD has been suggested in a report to inhibit angiogenesis through suppressing the expression of VEGFA and MMP-9, thus further restraining cancer growth." (PMID 30108661, 2018). "These four pathways were proteoglycans in cancer (ANK2, FASLG, HSPG2, PTPN11, STAT3, and VEGFA), HIF-1 signaling (ARNT, STAT3, and VEGFA), FoxO signaling (FASLG, SMAD4, and STAT3), and ECM-receptor interaction (HSPG2 and LAMA2)." (PMID 29300322, 2018). "For the three non-cancer diseases related genes (MMP2, VEGFA and CASP8), the percentage is just around 30%." (PMID 28340554, 2017). "The sequence of events is as follows: Hypoxia-induced activation of HIF-1 in cancer cells leads to the expression of VEGFA165, one of the 5 spliced isoforms of VEGFA." (PMID 28903453, 2017). "The top three non-cancer disease genes regulated by the co-functional module and mapped to the pathways are MMP2, VEGFA and CASP8, while for the cancers are BCL2, MDM2 and VEGFA." (PMID 28340554, 2017). "VEGFA was the first-identified member of the VEGF family and is expressed by various cell types including cancer cells." (PMID 29137669, 2017). "To test potential DNMT involvement in VEGFA‐driven miR‐128‐2 repression, and since DNA methyltransferases genes, DNMT3A, DNMT3B, DNMT1, are often coregulated and elevated in cancer stem‐like cells, we assayed all three methyltransferases." (PMID 28179359, 2017). "Protein expression of VEGFA and of its receptor VEGFR2 was almost abolished in cancers while VEGFB and VEGFD mRNA expression were significantly reduced." (PMID 29137669, 2017). "Subsequent in vivo studies revealed that miRNA-590-5p knockdown promoted cancer angiogenesis, growth and lung metastasis, whereas its overexpression attenuated CRC progression by regulating nuclear factor 90 (NF90)/VEGFA signaling axis." (PMID 29383201, 2017). "During the carcinogenesis of 26 kinds of cancers, averagely more than 70% of those cancers relate to the dysfunction of the three genes (BCL2, MDM2 and VEGFA)." (PMID 28340554, 2017). "It is known that vascular endothelial growth factor-A (VEGF-A) is one of the major inducers of angiogenesis and plays an important role in the pathogenesis and progression of various cancers." (PMID 26713602, 2016). "Of note, VEGFA was identified amongst the top 25 most discriminating biomarkers between CIN3 and cancer samples." (PMID 26701206, 2016). "Various cancer-related genes were also differentially expressed significantly, including BRAF, BRCA2, VEGFA, VEGFB, RET, PIK3CA, CTNNB1 and GNAS." (PMID 27350898, 2016). "Beyond the significant co-localization of ESSEs with the VEGF-A signaling pathway genes, including VEGFA itself, and the tendency of these genes to be upregulated in the cancer, we also characterized a particular site predicted to be a novel VEGFA enhancer." (PMID 26886256, 2016). "As shown, these miRNAs are active regulators of the expression of several cancer-related mRNAs, including ZEB1, ZEB2, VIM, VEGFA, NTRK3 and SPDEF, and most of the miRNAs are cancer-related." (PMID 24512620, 2014).
cancer (continued). "The result showed that, CDH1, VEGFA, PTPRF and CLDN7 were up-regulated in six cancer samples, and MMP2 was down-regulated in ten cancer samples, suggested that these genes, especially MMP2, were dysregualted in most UCB samples." (PMID 24622401, 2014). "Vascular endothelial growth factor-A (VEGF-A) is the main angiogenic mediator, and its levels have been correlated with poor prognosis in cancer." (PMID 23460876, 2013). "Therefore, VEGFA could be a potential target for cancer therapy." (PMID 23536895, 2013). "Vascular endothelial growth factor A (VEGFA), the key modulator of angiogenesis, is highly expressed in cancer tissue and correlates with its more aggressive features." (PMID 23203097, 2012). "The most important molecule for control of the angiogenic process is the vascular endothelial growth factor A (VEGFA), which is produced by cancer cells as a response to hypoxia." (PMID 22837657, 2012). "KEGG enrichment analysis showed that VEGFA and OPN participate in the ‘focal adhesion’ pathway (adjP=0.0002) and VEGFA along with FGF2, both participate in ‘pathways in cancer’ (adjP=0.0003)." (PMID 22895562, 2012). "Vascular endothelial growth factor (VEGF) family, of structurally related molecules including VEGFA, VEGFB, VEGFC, VEGFD and placental growth factor (PLGF), is one of the most potent angiogenic factors expressed in various human cancers." (PMID 22615958, 2012). "Transcript levels of growth factors and their receptors, such as VEGFA, MET, ESR1, EGFR, and HER2 were relatively undetectable in CTCs compared to cancer cell lines." (PMID 22586443, 2012). "We also have found that miR-29a can potentially target BCL2L2, VEGFA and CDK6, which are involved in cancer initiation and progression." (PMID 20668671, 2010). "These miRNAs target the tumour suppressor genes, PTEN, TP53INP1 and TP53INP2, and other proteins involved in cancer development and progression, such as BCL2L2, ERBB4, MAPK9, MCL1, MYCN, VEGFA and VEGFR1." (PMID 20668671, 2010). "Finally, our VM data (↑VE-cadherin/VEGFA, ↓ N-cadherin) align with reports that SLPI promotes vasculogenic mimicry in aggressive cancers." (PMID 41557653, 2026). "Within TME, hypoxia instigates cancer cells to secrete vascular endothelial growth factor A (VEGFA) leading to the development of irregular, non-uniform, and immature blood vessels." (PMID 40821116, 2025). "The most recent data on this topic have shown that MSLN can also drive macrophage polarization towards an immunosuppressive phenotype characterized by the secretion of VEGFA, ARG1, and S100A9, thereby stimulating cancer cell growth and weakening the immune response." (PMID 41335396, 2025). "• Exertion of anticancer effects through 3 major pathways: apoptosis (BIRC3, BIRC5, caspase-8, caspase-9, and PARP1), transcriptional dysregulation in cancer (CDKN1A, CDKN1B, MMP9, MYC, JUN, and RELA), and cancer progression (caspase-3, CCND1, CTNNB1, VEGFA, and Wnt-1)." (PMID 39181121, 2025). "The relative expression levels of PIK3CA, AKT, PTEN, VEGFA, NOTCH1, and HES1, as the key cellular signaling pathways involved in cancer biology, angiogenesis, and cell survival/proliferation, were investigated to determine the effects of SCC, DOK, and HaCaT products on fibroblasts." (PMID 40729037, 2025). "Additionally, GLO-1 expression demonstrated strong associations with both inhibitory and stimulatory ICPs, such as CD276, VEGFA, and HMGB1, across a majority of the analyzed cancer tissues." (PMID 40727469, 2025). "Finally, rats treated with anti-VEGFA (HD) experienced lower body weight gain than VEH rats, paralleling similar findings in cancer patients treated with BVZ." (PMID 40177629, 2025). "Core nodes include IL6, MYC, VEGFA, EGFR, and ESR1, all of which play essential roles in cancer development and may act as critical molecular regulatory hubs." (PMID 40045358, 2025).